TNF (tumor necrosis factor)
Diseases named in the same sentence as TNF in open-access papers (continued):
Sharing a sentence is not in itself a finding about the gene and the disease.
colitis (continued). "Notably and in line with the discussed role of TNF in the induction of intestinal GC synthesis, the injection of TNF triggered intestinal GC synthesis and resulted in the amelioration of oxazolone-induced colitis in mice." (PMID 31316505, 2019). "Consistently, histologic examination of colonic tissues revealed that activation of AhR with either Ficz or each of the two derivatives led to attenuation of colitis, which was associated with a significant reduction of IFN-γ and TNF-α and up-regulation of IL-22 RNA expression." (PMID 31031628, 2019). "During colitis, infiltrating monocytes are redirected toward a more pro-inflammatory macrophage phenotype, with elevated production of IL-1β, IL-23, and tumor necrosis factor (TNF)." (PMID 31031776, 2019). "In addition, FA-97 successfully prevented colitis by inhibiting the production of IL-1β, IL-6, TNF-α, IL-12, MIP-1α, and IL-17 in colons." (PMID 31969881, 2019). "Randomised controlled trials have demonstrated that infliximab and adalimumab, TNF-α antibody therapies, are effective for patients with moderate to severe colitis significantly improving mucosal healing and rates of disease remission hence decreasing the need for colectomy." (PMID 31488864, 2019). "The expression of TNF-α was highly correlated with the development of colitis." (PMID 30800169, 2019). "However, clinicians experienced in the use of ICB have noticed the often rapid and durable efficacy of anti-TNF agents in the treatment of colitis, sometimes with a single injection." (PMID 31727152, 2019). "Furthermore, the rats in the colitis group had significantly higher TNF-α concentrations than those in the control group (P < 0.05) at d5." (PMID 31221091, 2019). "Similarly, the peritoneal macrophages recovered from the rBmaCys-treated colitis mice were alternatively activated and displayed reduced expression of TNF-α and IL-6." (PMID 31683524, 2019). "Studies have shown that the thalidomide treatment reduce TNF-α, IL-6 and IL-1β production, and histological analysis showed considerable reduction in neutrophil infiltration and mucosal damage in colon homogenate of experimental colitis." (PMID 31920668, 2019). "In the future, TNF-α targeted therapy can be used to cure colitis in clinic." (PMID 31497551, 2019). "Thus, LL-F transformed with the pValac::anti-TNFα (LL-FT) plasmid was administered by gavage to a DSS-induced colitis in mice." (PMID 31238939, 2019). "Interestingly, Infliximab, a first-generation chimeric TNF blocking antibody is currently being used in the clinic to treat some of the irAEs, mainly colitis, sometimes triggered by ICI." (PMID 31417576, 2019). "Furthermore, there were reduced gut infiltrating macrophages and T cells in TRAIL-treated colitis mice; and the macrophage-derived cytokine, TNF-α, and T cell-derived cytokine, IL-17, were also significantly decreased." (PMID 31076664, 2019). "Therefore, the influencing mechanism of VSL#3 on TNF-α was explored in this paper through its treatment of rats with colitis, in order to provide a new option for the diagnosis and treatment of patients with the disease." (PMID 31497551, 2019). "Interestingly, apart from toxin-induced cytotoxicity, C. difficile infection leads to the activation of a cascade of mucosal pro-inflammatory cytokines, including IFNγ, TNFα, and IL1β, that result in recurrent colitis or ileitis." (PMID 30948494, 2019). "The levels of colonic IL-6 and TNF-α also decreased in Safranal-treated colitis mice." (PMID 31736758, 2019). "In C57BL/6 mice, β-sitosterol (20 mg/kg/day) administration for 56 days prevented the colon shortening (~8%) and reduced MPO activity in colon tissue (~35%), what led to a lower level of pro-inflammatory cytokines (IL-1β, TNF-α and IL-6) after colitis induction by high fat diet (60 Kcal% from fat)." (PMID 30987294, 2019).
colitis (continued). "However, after treatment with SASP and IN, the levels of IL-6, IL-8, and TNF-α decreased greatly compared with the colitis group, while the levels of IL-10 increased." (PMID 31726738, 2019). "However, the mechanisms of action of thalidomide are not yet entirely clear, its benefit has primarily been ascribed to its roles as an anti-TNF-alpha agent and reduce TNF-α, IL-6 and IL-1β production in colon homogenate of experimental colitis." (PMID 31920668, 2019). "Similarly to our study, NT reduced the level of TNF-α in the serum of rats with experimentally induced colitis." (PMID 31614422, 2019). "The colonic levels of TNFα were increased in the colitis group (P < 0.01)." (PMID 29849501, 2018). "Moreover, the data we have obtained in ADAM17ex/ex MEF show that the protection conferred by hypomorphic ADAM17 is not limited to DSS-induced colitis but also encompasses TNF-induced necroptosis." (PMID 29560122, 2018). "Recently a human mucosa colitis model was developed using TNFα and IL-1β." (PMID 30127744, 2018). "In the present study, we demonstrated that the maggot protein may ameliorate DSS-induced colitis by maintaining balanced immune responses through suppressing pro-inflammatory cytokines such as TNF-α and up-regulating IL-10 expression in colons and blood." (PMID 30393231, 2018). "In addition, mice with DSS-induced colitis exhibit a cytokine profile similar to colitis patients, including overproduction of proinflammatory cytokines TNF-α and IL-1β." (PMID 30166541, 2018). "Furthermore, treatment with these probiotics significantly suppressed blood LPS and TNF-α levels in mice with TNBS-induced colitis." (PMID 29760423, 2018). "To test whether blocking these pro-inflammatory cytokines can ameliorate colitis in mice, we examined the levels of TNF-α, IL-1β and IL-6 in the inflamed colonic tissue using ELISA." (PMID 29495327, 2018). "In addition, DALDA also showed anti-inflammatory responses in a mouse model of colitis through inhibition of T cell proliferation and cytokine (including TNFα) production." (PMID 29523156, 2018). "The serum IL-6 and TNF-α levels were greater in pAdipoR1-DSS mice with colitis." (PMID 29540173, 2018). "The expression TNF-α mRNA in mononuclear cells derived from TNBS-induced colitis was about 4 times higher than that of cells prepared from normal colonic tissues, and this is consistent with our current understanding of the molecular mechanisms that play a role in CD." (PMID 29862296, 2018). "In addition, in vitro atRA treatment of inflamed colonic mucosa from patients with ulcerative colitis and colitis-associated cancer modulates the LPS/TLR4/NFκB signaling pathway and decreases nitric oxide synthase 2 (NOS2) and TNF-α expression." (PMID 30158832, 2018). "We further found that GWT suppressed mRNA expression of tumor necrosis factor-α (TNF-α) and interleukin-12 (IL-12) in macrophage and reduced TNF-α mRNA expression in specimens with experimental colitis, which is in contrast to VSL#3 that enhanced TNF-α production." (PMID 29862296, 2018). "Therefore, both the circulating and colonic cell medium levels of IL-6 and TNF-α were higher in pAdipoR1 mice than in WT mice after acute colitis." (PMID 29540173, 2018). "Furthermore, it has been reported that the DSS-induced colitis model is characterized by increased serum levels of IL-6, IL-17, and TNF-α and decreased levels of IL-4 and IL-10." (PMID 30393231, 2018). "In addition, Bifidobacterium longum CH57 was found to attenuate colitis by inhibiting NF-κB signaling pathways and TNF-α expression." (PMID 29760423, 2018). "Further analysis demonstrated that IL‐35 recombinant protein may regulate inflammation through promoting the secretion of IL‐10 and inhibiting the expression of pro‐inflammatory cytokines such as IL‐6, TNF‐α and IL‐17 in acute colitis model." (PMID 29193791, 2018).
colitis (continued). "Furthermore, LycogenTM ameliorates the inflammation of dextran sodium sulfate (DSS)-induced colitis and cisplatin-induced renal injury by reducing the expression of pro-inflammatory cytokines, TNF-α and IL-1β." (PMID 29642620, 2018). "Anti-TNFα therapies are successfully used to treat diseases such as RA, colitis, and psoriasis." (PMID 29760711, 2018). "Proinflammatory cytokines TNFα and IL-1β (each 10 ng/mL) were used to induce colitis in mucosal strips, and the effects of Panx1 and P2X7R on cytokines-induced tissue damage were determined in the presence of the Panx1 channel blocker 10Panx1 (100 μM) and P2X7R antagonist A438079 (100 μM)." (PMID 30127744, 2018). "The elevated TNF-α level was significantly decreased in colitis mice treated with fargesin." (PMID 29880739, 2018). "While WT mice manage to deal with such TNFα expression, in mice with defects in autophagy such as Atg16L1-deficient mice, which cannot efficiently manage intracellular pathobionts, such TNFα expression drives chronic inflammation that manifests as severe colitis." (PMID 29534424, 2018). "In this study, we showed that treatment with SH significantly and dose-dependently decreased the plasma levels of IL-6, IL-1β and TNF-a, suggesting that SH may ameliorate colitis through alleviating inflammation." (PMID 30289941, 2018). "However, after treatment with sulfasalazine and TRYP, the levels of IL-6 and TNF-α decreased greatly comparing with the colitis group, while the levels of IL-1β and IL-10 changed insignificantly." (PMID 29724065, 2018). "A recent study reported that the administration of anti-TNF-α may be a strategy for managing colitis." (PMID 30289911, 2018). "Importantly our results demonstrated that MCC950 treatment significantly reduced IL-1β, IL-1α, IL17, IL6, IFN-γ, TNF-α and MIP1a in the colitis colon)." (PMID 29872077, 2018). "Additionally, many other investigators have reported that Gln therapy improves outcomes of experimental colitis by reducing oxidant injury, and inhibiting inflammatory processes such as NF-κB activation and TNF-α production." (PMID 29494494, 2018). "An in vivo study furthermore indicated that the administration of chemerin resulted in aggravation of DSS-induced colitis in mice by augmenting TNFα and IL-6 production, whereas a decrease in IL-10—producing anti-inflammatory macrophages could be detected." (PMID 30369924, 2018). "After combining this evidence, we hypothesized that TRYP exerted its protecting effect against DSS induced colitis via regulating the TNF-α/NF-κB and IL-6/STAT3 signaling pathways." (PMID 29724065, 2018). "The oral intake of a multi-fiber mix (MF) can reduce intestinal inflammation in a DSS-stimulated colitis model through the reduction of TNF-α, IL-6 and the increase of IL-10 expression, and it also increases the number of Treg cells in the mesenteric lymph nodes." (PMID 28654020, 2017). "For example, while IFX has been shown to reduce pathology and disease activity in the dextran sulphate sodium (DSS) colitis model 18, neither transcriptional inhibition of TNF‐α 22 nor genetic deficiency of TNF‐α has been shown to increase susceptibility." (PMID 27669117, 2017). "MPO activity, the TNF-α level, and the IL-1β level in the colitis rats were significantly higher than those in the control rats, and these effects were attenuated by acupuncture treatments at a neurogenic spot (Neuro-Sp), but not by stimulation of a nearby non-neurogenic site (Nearby site)." (PMID 29123119, 2017). "Moreover, colonic pro-inflammatory cytokines (TNF-α, IL-6, and IL-1β) induced by colitis were dramatically decreased by magnolol." (PMID 28726741, 2017). "Furthermore, the protein levels of TNF-α and IL-10 also exhibited a similar pattern in samples from the colitis mice." (PMID 28701721, 2017).
colitis (continued). "Infliximab, a novel anti-TNF-α compound that is used in the management of patients with refractory IBD, was suggested to be effective in cancer prevention with early intervention in animal models of colitis-associated CRC." (PMID 28852270, 2017). "In the present study, the levels of TNF-α, IL-6, and IL-17 were tested in colitis mice." (PMID 28824631, 2017). "Inulins inhibited the development of dextran sulfate sodium-induced colitis and colon cancer in mice; these fructans reduced the concentration of tumor necrosis factor alpha and prevented the formation of intestinal polyps, villous atrophy, and lymphoid hyperplasia." (PMID 28293641, 2017). "This difference may be the reflection of a weaker response to anti-TNFα therapy and/or a higher initial level of colitis." (PMID 28566745, 2017). "The induced TNFα deficiency with underlying colitis does not influence general health (viability and body weight) or clinical parameters (colon weight, colon length and histological colitis) when compared with the Winnie genotype alone." (PMID 28796256, 2017). "In particular, treatment with two specific MALT1 inhibitors, MI-2 and mepazine, dose-dependently attenuated the symptoms of colitis in mice through a decrease in protein and mRNA levels of colonic TNF, IL-1β, IL-6, IL-18, IL-17A, and IFN-γ pro-inflammatory cytokines." (PMID 28179906, 2017). "For instance, administration of cocoa FGM-derived polyphenols to DSS-induced colitis mice led to a partial but significant abrogation of intestinal length reduction, while levels of TNF-α and IL-1β significantly dropped in inflamed colon homogenates in comparison to untreated colitis animals." (PMID 28649251, 2017). "The murine model developed in this study incorporates a TNFα deficiency on a background of increased colitis that is closely representative of UC non-responders." (PMID 28796256, 2017). "thermophilus) to characterise the in vivo effects on a murine acute dextran sodium sulphate DSS-induced colitis model, and paralleled in vitro TNFα-cultured human HT-29 (human colon adenocarcinoma epithelial) cell effects on tight junction proteins (occludin, ZO-1) and MAPK signaling." (PMID 29065562, 2017). "To investigate how F991 reduced DSS-induced colitis, we used ELISA to analyze the levels of proinflammatory cytokines, including IL-6 and TNF-α, and the levels of the anti-inflammatory cytokine IL-10 in cultured supernatant from DSS-colitis tissues after F991 treatment on the 2nd, 4th, 6th days." (PMID 28701727, 2017). "In the colitis group, the intestinal levels of TNF-α were significantly increased." (PMID 29156831, 2017). "The AT of WT cells shortened colon length and increased IFN-γ and TNF-α expression; however, the AT of IFN-γ-deficient cells did not cause those changes, indicating that IFN-γ producing CS-exposed CD4+ T cells play a substantial role in inducing colitis." (PMID 29163466, 2017). "Furthermore, the expression of proinflammatory mediators such as TNF-α, IL-1β, IL-6 and iNOS mRNA in the colons of WT colitis mice was markedly upregulated on day 7 and significantly higher than those of p85α+/− colitis mice." (PMID 28733636, 2017). "TNF-α protein was higher in amebic colitis patients as assessed by immunohistochemistry." (PMID 28246365, 2017). "Mice with colitis had higher TNF-alpha levels compared to controls." (PMID 28465680, 2017). "Finally, we evaluated the level of IL-1β and TNF-α in colon tissues, and found a significant decrease of IL-1β and TNF-α in TLR4 deficient mice compared to control 7 days after the initiation of colitis." (PMID 27105524, 2016). "Rutin also, ameliorated TNBS-induced colitis in rats by inhibiting TNF-α-induced NF-kB activation." (PMID 27483999, 2016). "Additionally, MK2−/− mice are highly resistant to experimental colitis due to reduced IL-6 and TNF-α production, while IL-10 is later critical for taming colitis." (PMID 26998523, 2016).
colitis (continued). "Consequently, anti-TNF therapy has been used in human colitis with good effects for many patients, indicating that its multiple activities contribute strongly to chronic colitis." (PMID 26998523, 2016). "It has been shown that curcumin can attenuate TNF-α-induced oxidative stress, colitis in rats." (PMID 27544348, 2016). "TNF may exert various proinflammatory functions in colitis by binding to its receptors TNFR1 and TNFR2 followed by the intracellular activation of the transcription factor nuclear factor-κB (NF-κB)." (PMID 27347881, 2016). "Plasma levels of IL-1β, IL-6, IL-10, IL-17, TNFα, and IFNγ were detected in blood samples from all experimental mice group at two different time points, one corresponding to the acute phase of colitis (day 25), and one at the end of the recovery phase (day 37)." (PMID 26973525, 2016). "Induction of colitis increased mucosal concentration of IL-1β and TNF-α." (PMID 27598133, 2016). "In addition, the concentration of pro-inflammatory cytokines, in particular IFN-γ, TNF-α and IL-6 secreted by total LP cells in the colon, was two- to sixfold higher in IL-15-deficient mice with CD4+ T-cell-driven colitis compared with RAG2ko host mice." (PMID 26964669, 2016). "Our results showed that H-SN1 was able to significantly ameliorate the correlative symptoms of colitis in the mice, effectively alleviate the colonic pathological damage, and also to affect the downstream targets of the TNF/TNFR1 axis at both the gene and protein levels." (PMID 27158082, 2016). "The administration of TNF-α antibodies can effectively treat experimental rat colitis." (PMID 27544348, 2016). "IL-6, TNF-α, and IFN-γ are pathogenic mediators of murine colitis." (PMID 27110761, 2016). "Moreover, lower serum levels of interferon (IFN)-γ and tumor necrosis factor (TNF)-α were detected in G-MDSC exo-treated colitis mice." (PMID 26885611, 2016). "Herein, we show that colonic CCL25 expression is not only upregulated in patients with active colitis, but strongly correlates with endoscopic Mayo score and mucosal TNFα expression." (PMID 26873648, 2016). "Moreover, markedly lower levels of IFN-γ and TNF-α were detected in the serum of G-MDSC exo-treated colitis mice compared with that in other groups of colitis mice." (PMID 26885611, 2016). "TNF-α, as an important proinflammatory mediator, exerts a vital function in colitis." (PMID 27158082, 2016). "However, only the reduction of TNF-α concentration was statistically significant when compared to level observed in rats with colitis treated with saline." (PMID 27433160, 2016). "Moreover, the M2-BMDM recipient mice possessed less IL-6, TNF-α, and IL-1β in the serum than the colitis-only control mice." (PMID 27094081, 2016). "We have found that AMT-E exerts intestinal anti-inflammatory activity in the colitis by increasing mucus production, inhibiting neutrophil infiltration, down-regulating TNF-α, IL-1β, and IL-10, as well as suppressing COX-2 and iNOS expression in the mouse colon tissue." (PMID 27527191, 2016). "Data from experiments in vivo suggested that TNF-α might have both direct and indirect effects on the pathogenesis of colitis." (PMID 27158082, 2016). "Importantly, Src inhibitor dasatinib aggravated DSS-induced colitis by decreasing IL-10 while increasing TNF-α in vivo." (PMID 27188220, 2016). "Similarly, we also observed an inhibitory effect of L. acidophilus on colitis-mediated TNFα expression in mouse colon." (PMID 25973440, 2015). "Furthermore, GL-V9 successfully prevented colitis by inhibiting the elevated levels of IL-1β, IL-6 and TNF-α in serum and the high-production of IL-1β, IL-6, TNF-α, MIP-1α and IFN-γ in colons." (PMID 26327408, 2015). "In addition, receptor Y1-deficient mice have impaired APC function and consequently a decreased number of effector T cells, as well as a decreased MF production of TNF-α and IL-12, explaining the observed protective phenotype in experimental colitis." (PMID 26635804, 2015).